LAG3 (lymphocyte activating 3)
Diseases named in the same sentence as LAG3 in open-access papers (continued):
Sharing a sentence is not in itself a finding about the gene and the disease.
tumor (continued). "However, the TILs upregulated PD-1 and LAG-3 more potently and exhibited impaired effector functions in growing tumor compared to their counterparts in eradicated tumor." (PMID 39055715, 2024). "T cell exhaustion markers, such as T cell immunoglobulin and mucin-domain-containing protein-3 (TIM-3) and lymphocyte activation gene-3 (LAG-3), can also be targeted with antibodies to reduce T cell dysfunction and increase the number of activated tumor-killing T cells." (PMID 38275911, 2024). "Similar increases of CD39+ and LAG3+ in Ly6C+CD8+T cells were found when the Ly6C+CD8+T cells were incubated with TAMs sorted from NcDase−/− PyMT tumor compared to the T cells incubated with TAMs from WT PyMT tumor." (PMID 38302493, 2024). "Tumor cells express immune checkpoints such as the ligand of programmed death protein 1 (PD-L1), cytotoxic T lymphocyte-associated antigen-4, (CTLA-4), and lymphocyte activation gene 3 (LAG3), which inhibit the immune response." (PMID 38339348, 2024). "Coexpression of LAG-3 and PD-1 on tumor-infiltrating lymphocytes results in a cooperative immunosuppressive effect133that could be upheld to some degree even after ICI monotherapy targeting PD-1/PD-L1 resulting in resistance." (PMID 38806159, 2024). "Therefore, several markers of tolerance, such as PDL1, TIM3, and LAG3, were evaluated in tumor cells and at the TME by single and double IHC in 47 DLBCL cases with available material for analysis, in order to confirm gene expression findings." (PMID 38280007, 2024). "BA-treated tumours showed increased expression of genes linked to M1 TAM markers (Nfkbia, C7), effector memory T cells (Gzmk), and activated or exhausted T cells (Lag3, Tigit)." (PMID 38622286, 2024). "Importantly, only the triple anti-PD-1 + anti-LAG-3 + CBL-Bi combination showed a significant delay in tumor growth." (PMID 39030301, 2024). "However, some studies have indicated that the levels of CTLA-4, LAG-3, and TIM-3 originating from cells in patient tumor tissues are associated with survival times post-ICB treatment." (PMID 39528800, 2024). "Blocking LAG-3 can restore T cell function and increase tumour infiltration." (PMID 39337605, 2024). "LAG3 is found on activated immune cells and, like PD-1, stimulates tumor cell immune escape." (PMID 38396140, 2024). "Moreover, the binding of ABL-501 to LAG-3 and PD-L1 promoted dendritic cell (DC) activation and tumor cell conjugation with T cells that subsequently enhanced effective CD8+ T-cell responses." (PMID 38257366, 2024). "Furthermore, CB213 is a novel asymmetric bispecific antibody that blocks signaling through LAG-3 and PD-1 and inhibits tumor growth in MC38 models." (PMID 38581716, 2024). "It has also been shown that a combination of the inhibitors of these two immune checkpoints may enhance the anti-tumor response in comparison with the single inhibition of LAG-3." (PMID 38893211, 2024). "Further investigations are needed to confirm whether the tumor and the blood pathways here identified at baseline or early during treatment may represent true predictive biomarkers for anti-LAG-3 blockade-based immunotherapy." (PMID 38336861, 2024). "As a result, high LAG3 expression promotes tumor growth by inhibiting the immune microenvironment." (PMID 39872538, 2024). "Several studies have shown that LAG-3 plays an essential role in immunosuppression and tumor growth, indicating that inhibiting LAG-3 could have positive therapeutic effects in cancer treatment." (PMID 39660130, 2024). "Gal-3 has been identified as a noteworthy ligand for LAG-3 in the tumor microenvironment (TME)." (PMID 39331884, 2024). "In addition to baseline PD-L1 and LAG-3 expression, we sought to measure tumor burden kinetics longitudinally in the preoperative and postoperative setting as a more accurate indicator of therapeutic efficacy." (PMID 38504015, 2024).
tumor (continued). "As a first approach, we tested whether PDCD1 and LAG3 gene expression in tumor-immune infiltrate estimates correlated with immune cell infiltration by lymphoid (Fig. EV1A) and myeloid (Fig. EV1B) lineages." (PMID 39030301, 2024). "Similarly, the co-culturing of UPP1-overexpressing tumor cells with CD8 + T cells facilitated the transformation of CD8 + T cells towards a LAG3 + PDCD1+ exhausted T cell phenotype." (PMID 38331898, 2024). "Lymphocyte Activation Gene 3 (LAG3) is a key gene that regulates T cells, and its overexpression may lead to T cell depletion and ultimately poor tumor prognosis." (PMID 38582791, 2024). "only preliminarily demonstrated the effect of LSECtin and LAG-3 interaction on tumor cells." (PMID 39660130, 2024). "The expression of LAG3 on tumor-infiltrating lymphocytes (TILs) in some CRC tissues, where positive expression is associated with advanced tumor staging, MSI-H, and poor prognosis, may serve as a potential prognostic marker for CRC." (PMID 39839672, 2024). "The ligands of tumor cells bind to checkpoint proteins such as cytotoxic T-lymphocyte-associated protein 4 (CTLA-4), programmed cell death protein 1 (PD-1), and lymphocyte activation gene-3 (LAG-3)." (PMID 39441327, 2024). "Treg-infiltrated tumor tissues preferentially and consistently express LAG-3." (PMID 38627681, 2024). "In addition, the high expression of LAG-3 in a variety of tumors is correlated with prognosis of cancer patients, which shows its potential as an independent prognostic biomarker for tumor treatment." (PMID 39660130, 2024). "LAG-3 could be a marker for endogenous CD8+ T cells in the tumors that are specific for tumor antigens other than HA." (PMID 39343508, 2024). "Tumor-infiltrating CD8+ T cells in HBV-associated HCC were highly activated but dysfunctional, showing impaired cytotoxicity and exhaustion, with significantly increased expression of immune checkpoint molecules, such as PD-1, CTLA-4, LAG-3, and TIGIT." (PMID 38793588, 2024). "Given that the CD8+ T-cells in this model expressed high levels of LAG3, adding anti-LAG3 checkpoint blockade could further improve anti-tumor responses." (PMID 38476238, 2024). "One could assume that adding a LAG-3 inhibitor into this study may even make the tumor infiltration stronger than just the two combined." (PMID 39796650, 2024). "Thus, we conclude that LAG3 is higher on TH in tumor-sparse compared to tumor-rich regions but that the relative expression is highest on TC,57+ cells in tumor-rich regions." (PMID 39001353, 2024). "CTLA-4 and LAG-3 were induced in all patients after tumor interaction." (PMID 39475596, 2024). "However, there is currently an increasing diversity in treatment options, with new ICIs that enhance cancer treatment efficacy across a broad range of tumor types, such as anti-LAG-3 (Relatlimab), anti-TIGIT (Tiragolumab) and anti-TIM-3 mabs." (PMID 38612436, 2024). "Moreover, the results of IF-IHC assay indicated that the colocalization levels of Rab37, PD-1 and LAG3 were increased in tumor infiltrating CD8+ T cells in Rab37 WT group." (PMID 38321486, 2024). "The bioinformatics data demonstrate that targeting LAG-3 could reinvigorate these exhausted T cells, potentially restoring their cytotoxic function and enabling better tumor control." (PMID 39796650, 2024). "However, the expression of lymphocyte-activation gene 3 (LAG-3) protein was also distinctly higher in CD8+ T cells, specifically in the tumor-associated communities, in which ~30% of PD-1+ T cells were also LAG3+ following treatment with MRTX1257." (PMID 39485838, 2024). "Considering the capacity of tumor cells to promote sustained expression of IC, we hypothesized that tumor growth could impact the expression of LAG-3 in B-TILs, yet we only observed a transient elevation in 4T1 tumors." (PMID 38773133, 2024).
tumor (continued). "Therefore, future studies should focus on deeply exploring the specific mechanisms of action of LAG-3 inhibitors, including their roles within the tumor microenvironment and their interactions with other immune checkpoints and immune cells." (PMID 39743998, 2024). "The combined administration of anti-PD-1/PD-L1 and anti-LAG-3 antibodies displays a synergistic ability to inhibit tumor growth, as evidenced in phase 2/3 trials where the combination of relatlimab and nivolumab yielded significantly prolonged PFS compared to nivolumab alone." (PMID 38475778, 2024). "These included LAG3, which was significantly higher on TH,57− cells in tumor-sparse regions." (PMID 39001353, 2024). "In accordance with this, PD-1 and LAG-3 co-blockades increase many T-cell anti-tumor activities." (PMID 38590525, 2024). "The expression level of LAG-3 increases with the stimulation of tumor antigens." (PMID 39372416, 2024). "Apart from CTLA-4 and PD-1/PD-L1, LAG-3 has emerged as a promising target for tumor immunotherapy." (PMID 38375475, 2024). "However, in the TME, tumor cells often use this inhibitory function of LAG-3 to evade the immune system’s surveillance." (PMID 39660130, 2024). "The Adgrg1, Pdcd1, Osgin1, Lag3, and Chn2 were predominantly expressed in tumor-reactive T cells." (PMID 39243082, 2024). "Indeed, a key role for the hypoxia-inducible transcription factor 1 (HIF-1) in the induction of CTLA-4 and LAG-3 expression on tumor infiltrating CD8+ T cells, as well as of programmed cell death ligand-1 (PD-L1) on cancer cells has been demonstrated." (PMID 38175205, 2024). "High levels of LAG-3 expression correlate with tumor progression and a poorer prognosis." (PMID 39199689, 2024). "However, LAG-3′s role in immune evasion is carried out through its activation by corresponding ligands on tumor cells and downstream inhibitory signaling pathways that inhibit cytotoxic and cytokine production by CD8 T cells." (PMID 39796650, 2024). "For instance, in a mouse model of OSCC, blocking LAG3 was able to limit tumor growth, suggesting that LAG3 could be a viable target for immunotherapy." (PMID 39192980, 2024). "However, to our surprise, our results demonstrated that EPHX4 was significantly negatively correlated with CD274, PDCD1, IDO1 and LAG3, which all attenuate anti-tumor immunity and escape destruction by the immune system." (PMID 38663041, 2024). "Further data showed the LAG-3’s role in mediating an anti-tumor effect by binding to Class II MHC." (PMID 39796650, 2024). "mIHC staining showed that PD-1 and LAG3 were mainly localized in tumor mesenchyme." (PMID 39687617, 2024). "In addition to membrane receptors, soluble LAG‐3 exists, which impairs antitumor response in periphery blood and local tumor." (PMID 38469550, 2024). "Nevertheless, we assume sLAG3high patients might have high numbers of LAG3 expressing T lymphocytes in the tumor microenvironment, a known mechanism of evasion to anti PD-1 therapy." (PMID 38233492, 2024). "LAG-3 and PD-1 are inhibitory receptors on immune cells that can synergistically aid tumor evasion." (PMID 38627681, 2024). "Several checkpoint and inhibitory receptors, such as PD-1 (gene name: PDCD1), CTLA4, TIM-3 (HAVCR2), LAG3, CD39 (ENTPD1), CD160, KLRG1, CD96, BTLA, 2B4, and TIGIT, have been implicated in the reduction of immune activity and response in the tumor micro-environment." (PMID 39513882, 2024). "ICB drugs such as anti‐CTLA4/LAG3/TIGIT antibodies may be effective considering their high expression on tumor reactive T cells." (PMID 39136172, 2024). "In addition to increased intratumoral expression of Ltb, anti-PD-1 treatment elicited superior anti-tumor efficacy when compared to anti-LAG-3 and anti-TIM-3 therapy." (PMID 39623404, 2024).
tumor (continued). "LAG-3 and PD-1 have been detected to be co-expressed on CD4+ and CD8+ TILs in preclinical mouse tumor models, suggesting that their co-blockade of the LAG-3 and PD-1 signaling pathways can enhance the proliferation of tumor-specific CD8+ T cells and cytokine release." (PMID 38627681, 2024). "Prolonged exposure to antigen and inflammatory signals increases LAG-3 expression and leads to a state of exhaustion in T-cells, resulting in a reduced capacity to kill viruses and malignant cells, while inhibition of LAG-3 enhances viral control and anti-tumor immune responses." (PMID 38982041, 2024). "LAG-3 is highly expressed not only in T cells but also upregulated on NK cells, and this upregulation leads to suppression of both innate and adaptive immune functions in tumor patients." (PMID 39906665, 2024). "This interaction makes tumor cells more resistant in the face of the host immune system and therapeutic interventions, suggesting that strategies targeting LAG-3 and MHC-II interaction may have substantial clinical applications in cancer therapy." (PMID 39660130, 2024). "In the TME, TIGIT is frequently co-expressed on tumor-infiltrating lymphocytes (TILs), particularly in concert with other immune checkpoint molecules such as PD-1, lymphocyte activation gene-3 (LAG-3), and T-cell immunoglobulin and mucin-domain containing-3 (TIM-3)." (PMID 39152301, 2024). "For example, PD-1 + LAG-3 + CD8 + T cells are the mainstay of CT26 tumor-infiltrating lymphocytes." (PMID 38898505, 2024). "Furthermore, we included molecules such as CTLA-4 and LAG-3, which are important for optimal regulation and homeostasis of T cells within the tumor microenvironment." (PMID 38893183, 2024). "Furthermore, antibodies against PD-L1, TIM3, or LAG3 restored responses of HCC-derived T cells to tumor antigens, and combinations of these antibodies had synergistic effects." (PMID 37131179, 2023). "When tumor formation and progression caused end-stage abdominal distension in approximately 7–8 weeks, this condition coincided with the upregulation of PD1, Tim3, and LAG3 exhaustion markers." (PMID 37040183, 2023). "Notably, these LAG-3+ CD8 TEM cells accounted for ≥10% of the total tumor-infiltrating T cells in one quarter (7/28) of the samples." (PMID 37795090, 2023). "However, the combination of LAG3 and PD-1 inhibitors drastically restricted tumor proliferation compared with LAG3 or PD-1 inhibitor monotherapy in a mouse model." (PMID 38062416, 2023). "Lymphocyte-activation gene 3 (LAG-3) results in an immune outbreak of tumor cells." (PMID 37077370, 2023). "And XBP1, as a transcription factor, promoted the transcription of immunosuppressive molecules such as PD-1, TIM-3, and LAG-3 in CD8+ T cells, thereby causing CD8+ T cells to exhibit a functionally depleted and immunosuppressive state and promoting tumor progression." (PMID 37801479, 2023). "The density of LAG-3 positive cells increased significantly in HCC tumor tissues." (PMID 37304265, 2023). "Because we found very low levels of peripheral LAG-3 expression by CyTOF, we utilized scRNAseq as a highly sensitive orthogonal technique to profile and identify these rare circulating immune cell populations as they traffic to and from the tumor." (PMID 37795090, 2023). "Similarly, in mice transplanted with colorectal cancer cells, the combination of an anti-LAG-3 antibody plus an anti-PD-1 antibody revealed an enhanced control of the tumor growth as compared with the single treatments alone." (PMID 37511431, 2023). "Tebotelimab anti-tumor activity correlates with baseline immune activity in the TME as predicted by IFN-γ-regulated gene expression or LAG-3 expression levels, providing approaches to enrich for responsive patients that can be explored in future clinical studies." (PMID 37857711, 2023).
tumor (continued). "The consistent association of LAG3 expression levels and the infiltration of LAG3+ immune cells within the TME with tumor progression and unfavorable prognosis across diverse human tumor types strongly indicates the involvement of LAG3 in a PD-1-like tumor immune escape mechanism." (PMID 38041068, 2023). "The authors subjected the extracranial and intracranial tumour specimens to immunophenotypic staining for programmed death ligand 1 (PD-L1), programmed cell death receptor 1 (PD-1), lymphocyte activation gene-3 (LAG-3) and T cell immunoglobulin and domain-mucin containing-3 (TIM-3)." (PMID 36980583, 2023). "Like PD-1, LAG-3 prevents anti-tumor T cell activity and contributes to T cell exhaustion." (PMID 37857711, 2023). "For tumor lesions, increasing the mass dose also resulted in a decrease in tumor-to-plasma ratios, which demonstrates target specificity, and is consistent with LAG-3 saturation at these doses." (PMID 36859619, 2023). "Importantly, A2AR inhibition was found to exhibit the most pronounced effects during CD8+ effector T cell activation, thus remarkably reducing PD-1 and LAG-3 expression at the draining lymph nodes of tumor bearing mice." (PMID 36859386, 2023). "However, tumor-specific T cells infiltrating primary tumors progressively downregulate both Cxcr3 and Klrg1 while upregulating exhaustion markers PD-1 and Lag-3." (PMID 36472588, 2023). "By contrast, more LAG-3+ cells were found in the CD4 than in the CD8 T cells in the tumor." (PMID 37174080, 2023). "High interferon signaling could induce high expressions of PD-L1 and MHC-II in tumor cells, which bind to PD-1 and LAG3 on the surface of T cells, respectively, and results in reduced CAR-T cell expansion and increased exhaustion." (PMID 37158921, 2023). "Moreover, upregulation of LAG-3 expression on tumor-infiltrating lymphocytes (TILs) has been suggested as a resistance marker to anti-programmed death 1 (anti-PD-1) treatment in patients who initially respond well to this treatment." (PMID 36859619, 2023). "The higher expression of immune checkpoint molecules, including LAG3, in the immune hot tumours may suggest potential benefits of ICB immunotherapy." (PMID 37258531, 2023). "Increased infiltration of CAR T-cells into tumor.Reduction in tumor infiltrating Tregs.Suppression of co-inhibitory receptor (PD-1 & LAG3) expression on T cells.Promotes expression of T-cell recruiting chemokines in tumor cells (CXCL9, CXCL10) and CXCR3 receptors on CAR T cells." (PMID 36949946, 2023). "We identified tumor-infiltrating T cells with a triple-positive PD-1, LAG-3 and TIM-3 phenotype." (PMID 37174080, 2023). "Furthermore, CTLA4 and LAG3 were negatively expressed in tumor-infiltrating lymphocytes, while CD96 and HAVCR2 were highly expressed in cluster CD8_1, indicating functional exhaustion of cells in this cluster within TME." (PMID 37533434, 2023). "Galactose lectin-3 (galectin-3) and liver sinusoidal endothelial cell lectin (LSECtin), ligands for LAG3, are also important immunosuppressive checkpoints expressed on the surface of a variety of tumor cells and are involved in the regulation of CD8+ T-cell function." (PMID 37055849, 2023). "Lower levels of LAG3 expression were detected in tumor tissues compared to control tissues." (PMID 38115039, 2023). "Conversely, anti-LAG-3 alone showed comparable tumor growth inhibition to AU-011 alone." (PMID 36997666, 2023). "In preclinical models, dual inhibition of LAG3 and PD-1 showed synergistic anti-tumor activity." (PMID 37880788, 2023). "Thereby, a constant antigen stimulation of the T cells in the tumor microenvironment (TME) leads to a high expression of LAG3 and of other co-inhibitory receptors on T cells, such as PDCD1, promoting immune escape in tumors and exhaustion of T cells that lose their effector functions." (PMID 37215135, 2023). "NK cells express the immune checkpoints, PD-1 and LAG-3, and immune checkpoint blockade may enable NK cell anti-tumor responses." (PMID 38090565, 2023).